C16orf82 (chromosome 16 open reading frame 82)
Synonyms: TNT
Gene: Protein-coding gene on chromosome 16 (27,066,927 to 27,069,166, forward strand). Ensembl gene ENSG00000234186.
Genetic constraint (gnomAD): Loss-of-function variants: 0 observed, 0.15 expected, observed/expected ratio (o/e) 0, 90% interval 0 to 1.88. That is too few expected variants to judge how well the gene tolerates losing a copy. Missense variants: 176 observed, 184.33 expected, observed/expected ratio (o/e) 0.95, 90% interval 0.84 to 1.08. Synonymous variants: 82 observed, 75.53 expected, observed/expected ratio (o/e) 1.09, 90% interval 0.91 to 1.3.
Homologues: Orthologues: chimpanzee C16H16orf82 (98% identical), macaque C20H16orf82 (85% identical), pig C16orf82 (55% identical), dog C16orf82 (52% identical).